ING5 (inhibitor of growth family member 5)
Diseases named in the same sentence as ING5 in open-access papers (continued):
Sharing a sentence is not in itself a finding about the gene and the disease.
tumor (continued). "Besides, miR-196b-5p knockdown inhibited tumor growth, whereas ING5 knockdown elevated it in vivo." (PMID 32308564, 2020). "Hence, it is quite possible that modulating miR-24 may increase ING5 expression and subsequently activate the anti-tumor effects of ING5." (PMID 28490335, 2017). "In addition, it was reported that ING5 could affect adhesion, migration, invasion, proliferation and apoptosis of tumor cells." (PMID 28086946, 2017). "Thus the findings suggest that in these tumor cells ING5 expression is essential for proliferation." (PMID 25860957, 2015). "Moreover down-regulation or cytoplasmic re-localization of ING5 has been observed in a number of tumors, suggesting that ING5 might function as a tumor suppressor." (PMID 25860957, 2015). "However, whether these effects of ING5 on DNA replication and S-phase progression contribute to its tumor suppressor or oncogenic functions needs to be further studied." (PMID 21750715, 2011). "Inhibitor of growth family member 5 (ING5), a class II tumor suppressor, is translationally targeted by miR-196, miR-196a, miR-196b-5p, miR-193a-3p, and miR-27-3p." (PMID 39201509, 2024). "The inhibitor of growth (ING), a tumor suppressor, can be divided into three categories: one is ING1 and ING2, and ING4 and ING5 are classified as type II, while ING3 is different from other members." (PMID 30386928, 2019). "The tumour suppressor roles of ING1 and ING2 have been well established whereas candidate tumour suppressor status remains for ING3, ING4, and ING5." (PMID 31905726, 2019). "It has been reported that ING5 inhibit proliferation, cell cycle progression, migration and invasion and epithelial-mesenchymal transition (EMT) of tumor cells." (PMID 28915612, 2017). "ING5, one of the ING family genes and as a transcriptional co-activator, has been demonstrated to play important roles in the development of tumor." (PMID 28086946, 2017). "It was earlier shown that in the presence of the human tumour suppressor proteins ING4 and ING5, Jade-1 targets the chromatin through interaction with H3K4me3 modifications." (PMID 24267901, 2013). "As a Class II tumor suppressor, ING5 contains nuclear localization signal, plant homeodomain, novel conserved region, and leucine zipper-like domains." (PMID 36425530, 2022). "ING5, the last member of Inhibitor of Growth (ING) family, is a well-known tumor suppressor." (PMID 32308564, 2020). "In addition, we have found a significant reduction of ING5 expression in AML patients, further supporting a function of ING5 as a tumor suppressor." (PMID 25938545, 2015). "ING5 is the new member of the family whose actual role in tumor suppression is not known." (PMID 25938545, 2015). "For the candidate tumour suppressor genes ING3 and ING5, no mutant mouse models have been described so far to support or weaken their tumour suppressor gene status and to further investigate their function in vivo." (PMID 31905726, 2019).
cancer (37 papers, 2011 to 2026). A tumor composed of atypical neoplastic, often pleomorphic cells that invade other tissues. "ING5 is associated with various cancer types and rare diseases involving neuronal abnormalities, such as Ohdo Syndrome." (PMID 37953885, 2023). "Histologically, conditional ING5 abrogation causes gastric dysplasia and cancer, and increases chemically-induced gastrointestinal carcinogenesis." (PMID 36425530, 2022). "The overexpression and nucleocytoplasmic translocation of ING5 are seen during carcinogenesis, and ING5 expression was inversely associated with aggressive behaviors and poor prognosis in a variety of cancers." (PMID 36425530, 2022). "Histologically, ING5 abrogation in gastric stem-like and pdx1-positive cells causes gastric dysplasia and cancer, and conditional ING5 knockout in pdx1-positive and gastric chief cells increases MNU-induced gastric carcinogenesis." (PMID 36425530, 2022). "Previous experiments in vitro indicated that ING5 functions to maintain stem cell character in normal and in cancer stem cells." (PMID 39787145, 2025). "ING5 was not only highly expressed in these cancer stem cells and lost upon differentiation, but it also promoted self-renewal, prevented lineage differentiation, and increased stem cell pools." (PMID 39787145, 2025). "Inhibitor of growth 5 (ING5) has been reported to be involved in the malignant progression of cancers." (PMID 39247819, 2024). "ING5 is a tumor-suppressor gene that is downregulated in several types of cancer, including thyroid, colorectal, breast, and lung." (PMID 37810885, 2023). "ING5 suppresses aggressive phenotypes of various cancer cells via EGFR/PI3K/Akt, IL-6/STAT3, Akt/NF-κB/NF-κB/MMP-9 or IL-6/CXCL12 pathway." (PMID 36425530, 2022). "Evidentially, exosomal miR‐196a from cancer‐associated fibroblasts binds to CDKN11B and ING5 and confers cisplatin resistance via G1/S resistance and apoptosis regulation." (PMID 34469038, 2021). "Some studies have suggested the importance of ING5 in maintaining stemness in various stem cell types, including in cancer stem cells." (PMID 34067525, 2021). "The nucleocytoplasmic translocation of ING5 protein were observed in HNSCC, gastric, colorectal and lung cancers, and positively associated with their aggressive behaviors or worse prognosis." (PMID 29137236, 2017). "We then focused on PI3K/Akt and STAT3 signaling pathways, both of which have been extensively studied to promote cancer cell proliferation and invasion, to confirm the activation of the two pathways by ING5 knockdown." (PMID 28903339, 2017). "The hypoexpression and nucleocytoplasmic translocation of ING5 protein were observed in HNSCC, gastric, colorectal and lung cancers, and positively associated with their aggressiveness." (PMID 29262575, 2017). "Nuclear ING5 expression was higher than benign and borderline tumors than in the normal ovary and primary cancer (p < 0.05)." (PMID 29262575, 2017). "Previous data showed that ING5 decreased the capability of invasion and migration in lung, breast and colorectal cancers." (PMID 29262575, 2017). "To analyze the signaling pathways and mechanisms of ING5 knockdown-induced cancer invasiveness, we did antibody array with 43 kinase phosphorylation sites." (PMID 28903339, 2017). "We used ING5 overexpression and knockdown cells lines described previously to further confirm ING5 function in cancer invasiveness." (PMID 28903339, 2017). "Altered ING5 expressions have been reported in certain cancers including gastric carcinogenesis, human head and neck squamous cell carcinoma, and oral squamous cell carcinoma, functioned as a suppressor by inhibiting cell growth and inducing apoptosis." (PMID 26497554, 2015).
cancer (continued). "ING5 was reported to be a tumor suppressor gene that inhibited cell growth and induced apoptosis in certain cancers, but the effects of ING5 in HCC are poorly understood." (PMID 26497554, 2015). "This is consistent with previous reports in other cell types that overexpression of ING5 in cancer cells resulted in reduced colony formation." (PMID 21750715, 2011). "However, in a few studies changes of ING5 at mRNA and protein levels are reported inconsistently or being upregulated in cancer tissues." (PMID 36056353, 2022). "In addition to growth-inhibitory effects, ING5 is shown to regulate differentiation of stem cells such as epidermal stem cells and cancer stem cells." (PMID 36056353, 2022). "And miR-196b-5p bind to the 3’UTR region of ING5, which induces apoptosis in cancer cells." (PMID 33996574, 2021). "Furthermore, ING5 contributes to cancer formation and disease progression in gastric carcinomas and colorectal cancer, according to previous literature." (PMID 31390718, 2019). "Moreover, in mouse xenograft models, niclosamide was found to impair ING5 knockdown-stimulated cancer cell metastasis as well." (PMID 31390718, 2019). "ING5 protein was less expressed in primary cancer than normal ovary by Western blot (p < 0.05)." (PMID 29262575, 2017). "Taken together, these studies indicated that ING5 might reverse the aggressive phenotypes of various cancer cells and be employed as a potential target of gene therapy." (PMID 29262575, 2017). "ING5 protein was less expressed in primary cancer than normal ovary (p < 0.05)." (PMID 29262575, 2017). "To investigate whether ING5 inhibits cancer cell invasiveness by targeting both signaling pathways, we treated A549 shControl and A549 shING5 cells with ZSTK474 and Niclosamide, respectively." (PMID 28903339, 2017). "Different from the result owing to the different types of cancer, our results indicated ING5 was targeted by miR-1307, yet we could also use the similar method to prove their correlation." (PMID 28086946, 2017). "To investigate whether ING5 decreased cancer invasion by inhibiting EMT, we analyzed mRNA level of several EMT markers in ING5-overexpressing and control A549 cells." (PMID 25938545, 2015). "ING5 was more expressed in elder than younger cancer patients (p < 0.05)." (PMID 25980581, 2015). "Therefore, ING5 may be a good molecular target for the gene therapy to reverse the aggressive phenotypes of cancer cells if its chemoresistance might be ameliorated or prevented." (PMID 29137236, 2017). "qRT-PCR validation using ING5 control and overexpression cells (A549 ING5), and ING5 shControl and knockdown A549 cells (A549 shING5), were carried out for 30 selected genes which were known to be cancer-related genes out of genes downregulated by ING5 overexpression." (PMID 25938545, 2015). "Meanwhile, Kaplan-Meier plotter showed that ING5 mRNA expression was negatively correlated with overall survival (OS), progression-free (PFS) survival, and post-progression survival (PPS) rates of cancer patients (P<0.05)." (PMID 35747809, 2022). "In agreement with ING4 and ING5 being required for normal cell cycle progression, we observed that ING3 is also required for cellular proliferation of cancer cells." (PMID 29381681, 2018). "The hypoexpression of nuclear ING5 protein and its cytoplasmic translocation were observed in oral squamous cancer, HNSCC, colorectal and gastric cancers." (PMID 25980581, 2015).
cancer (continued). "Moreover, ING5 overexpression was demonstrated to cause the differentiation of SGC-7901 cells evidenced by enhanced ALP activity and remarkable tight junctions, supporting a higher expression of ING5 protein in intestinal-than diffuse-type carcinomas by Western blot and immunohistochemistry." (PMID 25980581, 2015). "Furthermore, ING5 is known to regulate signaling pathways like AKT and inflammatory pathways playing role in development and progression of cancers." (PMID 36056353, 2022). "There was a negative correlation between ING5 mRNA expression and the overall or progression-free survival time of the cancer patients with Grade 2, Grade 3, and stage I cancer (p < 0.05)." (PMID 29262575, 2017). "According to Kaplan–Meier plotter, there was a negative correlation between ING5 mRNA expression and the overall or progression-free survival time of the patients with Grade 2, Grade 3, and Stage I cancer (p < 0.05)." (PMID 29262575, 2017).
adenocarcinoma (2 papers, 2016 to 2017). A common cancer characterized by the presence of malignant glandular cells. "Immunostaining revealed that ING5 expression was strong in ovarian adenoma, borderline tumor, adenocarcinoma and endometriod carcinoma, but not or very weak in normal fiber." (PMID 29262575, 2017).
ING5 also shares sentences with these, for which no sentence is quoted: melanoma (2 papers); tongue squamous cell carcinoma (2); ameloblastoma (1); astrocytoma (1); autism (1); benign tumors (1); Central Giant Cell Granuloma (1); dysplasia (1); esophageal cancer (1); leukemia (1); lung (1); lymphoma (1); metastatic tumors (1); mucinous adenocarcinoma (1); Obesity (1); oral cancers (1); pneumonia (1); schizophrenia (1); small cell carcinoma (1).